ART3 (ADP-ribosyltransferase 3 (inactive))
Synonyms: ARTC3
Tractability: Antibody: its Gene Ontology location is reachable by antibodies, with high confidence; UniProt places it where antibodies can reach, with medium confidence; UniProt predicts a signal peptide or a membrane-spanning region.
Gene: Protein-coding gene on chromosome 4 (76,011,184 to 76,114,094, forward strand). Ensembl gene ENSG00000156219.
Subcellular location: Cell membrane
Subcellular location (Human Protein Atlas): End piece; Principal piece
Pathways (Reactome):
Metabolism of proteins: Post-translational modification: synthesis of GPI-anchored proteins
Gene Ontology:
Molecular function: NAD+ poly-ADP-ribosyltransferase activity; NAD+-protein-arginine ADP-ribosyltransferase activity
Cellular component: extracellular exosome; extracellular region; plasma membrane
Genetic constraint (gnomAD): Loss-of-function variants: 44 observed, 41.09 expected, observed/expected ratio (o/e) 1.07, 90% interval 0.84 to 1.38. The upper end of that interval is the gene's LOEUF score, 1.38, which puts it in group 5 of 6, group 1 being the genes least tolerant of losing a copy. Missense variants: 402 observed, 433.11 expected, observed/expected ratio (o/e) 0.93, 90% interval 0.86 to 1.01. Synonymous variants: 132 observed, 154.79 expected, observed/expected ratio (o/e) 0.85, 90% interval 0.74 to 0.99.
Homologues: Orthologues: chimpanzee ART3 (98% identical), macaque ART3 (93% identical), dog ART3 (74% identical), pig ART3 (74% identical), guinea pig ART3 (72% identical), rabbit ART3 (68% identical), rat Art3 (56% identical), mouse Art3 (53% identical), tropical clawed frog art5 (22% identical), zebrafish si:ch211-145b13.6 (15% identical). Paralogues in human: ART5 (27% identical), ART1 (23% identical), ART4 (18% identical).
Diseases named in the same sentence as ART3 in open-access papers:
ART3 is named in the same sentence as 33 diseases in open-access papers, as found by Europe PMC text mining. Sharing a sentence is not in itself a finding about the gene and the disease. The quoted sentences say what the papers report.
triple-negative breast carcinoma (6 papers, 2016 to 2025). An invasive breast carcinoma which is negative for expression of estrogen receptor (ER), progesterone receptor (PR), and human epidermal growth factor receptor 2 (HER2). "Forced expression of ART3 stimulates proliferation of triple-negative breast cancer cells and modulates triple-negative breast carcinogenesis via activation of Akt and ERK pathways." (PMID 36755247, 2023). "Studies on cancer showed that ART3 can be used as a triple-negative breast cancer (TNBC) marker, and its overexpression in TNBC cells can reduce their apoptosis rate." (PMID 33466297, 2021).
breast carcinoma (5 papers, 2016 to 2025). "In this study, we firstly determined that the expression of human ecto-ADP-ribosyltransferase 3 (ART3) is significantly associated with the basal-like breast cancer subgroup, which is largely overlapped with TNBC, through analyzing published data sets." (PMID 27374177, 2016). "We also showed the association of ART3 protein levels with TNBC using an immunohistochemical assay in human breast cancer specimens." (PMID 27374177, 2016). "The association of ART3 mRNA expression with basal-like breast cancers prompted us to study whether ART3 might be overexpressed in TNBC." (PMID 27374177, 2016). "Overexpression of ART3 in MDA-MB-231 breast cancer cells increased cell proliferation, invasion, and survival in vitro and growth of xenograft tumors." (PMID 27374177, 2016). "In order to further elucidate the clinical relevance of ART3 in breast cancer, we performed Kaplan-Meier survival analysis." (PMID 27374177, 2016). "Conversely, knockdown of ART3 in breast cancer cells inhibited cell proliferation and invasion." (PMID 27374177, 2016). "Our data indicated that high levels of ART3 are correlated with worse prognosis in breast cancer." (PMID 27374177, 2016). "Of note, in two ER+ breast cancer cell lines, ART3 expression were almost undetectable." (PMID 27374177, 2016). "However, biological functions as well as molecular mechanisms of these genes in breast cancer should be further investigated, as only 8 and 2 papers were available when PubMed was searched with keywords “breast cancer + HORMAD1” or “breast cancer + ART3,” respectively." (PMID 34108519, 2021). "Using a cohort of fixed breast cancer samples, immunohistochemistry detected 3 in 39 ER+ samples, 2 in 31 ER-/Her-2+ samples, and 28 in 43 TNBC samples were positive for ART3 expression." (PMID 27374177, 2016). "In this study, we found that ART3 mRNA was overexpressed in human TNBC compared with non-TNBC and correlated with a shorter survival for breast cancer patients." (PMID 27374177, 2016). "ART3 mRNA was increased in nearly half of basal-like (49%) and very few HER2-amplified (5%) breast cancers, but not increased in any luminal A or B breast cancers." (PMID 27374177, 2016).
Azoospermia (2 papers, 2020 to 2021). Absence of any measurable level of sperm,whereby spermatozoa cannot be observed even after centrifugation of the semen pellet. "The mutations in ART3 cause nonobstructive azoospermia, but the specific mechanism is not clear." (PMID 32450814, 2020). "ART3 was also detected in human spermatocytes and is significantly related to human nonobstructive azoospermia." (PMID 33466297, 2021).
Alzheimer disease (1 paper, 2024). A progressive, neurodegenerative disease characterized by loss of function and death of nerve cells in several areas of the brain leading to loss of cognitive function such as memory and language. "Moreover, in a genome-wide association study investigating endophenotypes associated with pre-diagnostic stages of Alzheimer’s disease, the rs79955867 C > T single nucleotide polymorphism (SNP) mapping to a CpG site within the ART3 locus was associated with decreased hippocampal volume." (PMID 38417824, 2024).
cervical cancer (1 paper, 2025). A primary or metastatic malignant neoplasm involving the cervix. "Eventually, we obtained a seven-mRNA–lncRNA gene cluster (four mRNAs: ART3, HRG, MAPT, and SYTL5; three lncRNAs: AC011239.1, AC125616.1, and RUVBL1.AS1) that was mostly relevant to LNM of cervical cancer." (PMID 40444278, 2025). "Among these transcripts, AC125616.1, HRG, MAPT, RUVBL1.AS1, and SYTL5 were found to be upregulated, while AC011239.1 and ART3 were downregulated in cervical cancer patients with LNM compared to those without it." (PMID 40444278, 2025).
congenital heart disease (1 paper, 2024). A heart disease that is present at birth. "Although shared genes like TMTC1, ART3, and ARHGAP24 are shown to contribute to different congenital heart disease subtypes, they actually play different roles across subtypes." (PMID 39202774, 2024).
dilated cardiomyopathy (1 paper, 2024). Cardiomyopathy which is characterized by dilation and contractile dysfunction of the left and right ventricles. "In cardiomyocytes, distinct genes such as TMTC1, ART3, ARHGAP24, SHROOM3, and XIST were linked to dilated cardiomyopathy, Neo-Hypoplastic Left Heart Syndrome, hypertrophic cardiomyopathy, HF-Hypoplastic Left Heart Syndrome, and Tetralogy of Fallot, respectively." (PMID 39202774, 2024).
hepatocellular carcinoma (1 paper, 2016). A malignant tumor that arises from hepatocytes. "To date, there is only one report in this regard, indicating that ART3 might increase the tumor size of hepatocellular carcinoma (HCC) with loss of heterozygosity (LOH)." (PMID 27374177, 2016).
influenza (1 paper, 2019). An acute viral infection of the respiratory tract, occurring in isolated cases, in epidemics, or in pandemics; it is caused by serologically different strains of viruses (influenzaviruses) designated A, B, and C, has a 3-day incubation period, and usually lasts for 3 to 10 days. "Furthermore, RNAseq identified altered expression of ART3 and KCNH7 genes that were not previously detected in influenza transcriptomes." (PMID 31461941, 2019).
medulloblastoma (1 paper, 2024). A malignant, invasive embryonal neoplasm arising from the cerebellum. "While not directly related to neurocognition, the ART3 protein, a known tumour marker, has been observed in the cerebrospinal fluid of recurrent medulloblastoma patients, and expression of this gene has also been associated with survival after diagnosis with medulloblastoma." (PMID 38417824, 2024).
melanoma (1 paper, 2021). A malignant, usually aggressive tumor composed of atypical, neoplastic melanocytes. "The overexpression of ART3 in melanoma cells was shown to promote cell migration." (PMID 33466297, 2021).
neuroendocrine tumors (1 paper, 2020). "Among these, known biomarkers for MB (FSTL5), and other tumor types such as neuroendocrine tumors (ENO2, FMOD, ART3, COL6A3) and PIP, were found to be significantly up-regulated (dark green)." (PMID 32466393, 2020).
neurofibromatosis (1 paper, 2025). A hereditary neoplastic syndrome in which tumors grow in the nervous system. "To illustrate differences in TG-specific B coordination networks between SC sub-types, even for shared TGs, we examine TG ART3 (ADP-Ribosyltransferase 3) that colocalizes with neurofibromatosis (NF: characterized by the formation of NS-related tumors) with a 68% probability." (PMID 40260118, 2025).
schizophrenia (1 paper, 2024). A major psychotic disorder characterized by abnormalities in the perception or expression of reality. "In a recent large meta-analysis, methylation at cg22301128 located within the gene body of ART3 was reported to be significantly hypomethylated in blood samples from cases with established schizophrenia compared to controls." (PMID 38417824, 2024).
tumor (12 papers, 2016 to 2026). "Among ARTC family, ART1 and ART3 modulate the phosphoinositide 3-kinase (PI3K)/protein kinase B (AKT) pathway, influencing angiogenesis, tumor growth, and immune evasion via cluster of differentiation 8+ (CD8+) T-cell apoptosis." (PMID 41930181, 2026). "According to the Expression Atlas, the hypoxia-associated molecules CALB1, DDAH1, GAP43 and GPR37, as well as the tumor markers ART3, ENOL2 and FMOD and the tumor promoter NTNG1, are typically expressed in hematopoietic stem cells." (PMID 32466393, 2020). "Proteome profiling identified characteristic tumor markers, including FSTL5, ART3, and FMOD, and revealed a strong prevalence of anti-inflammatory and tumor-promoting proteins characteristic for alternatively polarized myeloid cells in MB samples." (PMID 32466393, 2020). "In fact, researchers have found that proteomic analysis identified typical tumor markers, including FSTL5, ART3, and FMOD, and revealed the prevalence of anti-inflammatory and tumor-promoting proteins that are characteristic of myeloid cells in CSF from patients with MB." (PMID 34977115, 2021). "To further evaluate the effect of ART3 overexpression on TNBC cells in vivo, we established xenograft tumor models for MDA-MB-231 cells with/without ART3 overexpression." (PMID 27374177, 2016).
cancer (7 papers, 2014 to 2025). A tumor composed of atypical neoplastic, often pleomorphic cells that invade other tissues. "Furthermore, three genes—Cxorf65, SSTR3, and ART3—had a testis-associated expression pattern and might represent novel Cancer/Testis antigens." (PMID 35145509, 2021). "This study establishes the foundation for further exploration of the biological function and mechanism of ART3 in cancer cells." (PMID 27374177, 2016).
psychiatric disorder (1 paper, 2024). A disorder characterized by behavioral and/or psychological abnormalities, often accompanied by physical symptoms. "Also, DNA methylation at cg12159836 within the 5ʹUTR of ART3 was also observed to be significantly lower in saliva from maltreated children, who go on to have increased risk of psychiatric disorders, compared with controls." (PMID 38417824, 2024).
ART3 also shares sentences with these, for which no sentence is quoted: acute myocardial infarction (1 paper); cardiac hypertrophy (1); cholera (1); colorectal cancer (1); diphtheria (1); esophageal cancer (1); hypertrophic cardiomyopathy (1); hypoplastic left heart syndrome (1); infection (1); Obesity (1); ovarian carcinoma (1); prostate carcinoma (1); sexually transmitted infections (1); Tetralogy of Fallot (1); viral infections (1); Whooping cough (1).